CD5 (CD5 molecule)
Diseases named in the same sentence as CD5 in open-access papers (continued):
Sharing a sentence is not in itself a finding about the gene and the disease.
diabetes (7 papers, 2019 to 2024). "We speculated that the higher frequency of CD5+ expressing B subsets in the diabetes group could be associated with the anti-inflammatory capacity of CD5+ B cells." (PMID 38134245, 2024). "Our results suggest that CD163+ monocyte-mediated T cell activation was down-regulated in individuals with diabetes-related complications, due to the increased CD5 and decreased CD86 expression." (PMID 39337580, 2024). "We observed an increased expression of the gene CD5 in CD163+ monocytes in individuals with diabetes-related complications." (PMID 39337580, 2024). "Neither untreated CD5 KD or WT mice nor dox-treated WT (WTdox) mice showed any signs of weight loss or disease beyond the expected diabetes phenotype." (PMID 35720357, 2022). "Correlation analysis showed that IMT was positively correlated with systolic blood pressure, protein/creatinine ratio and diabetes (P < 0.05), and were negatively correlated with CD19(+)CD5(+) and CD19(+)CD5(−) B lymphocytes (P < 0.05)." (PMID 34844574, 2021). "In mice, FasL can be induced by TLR4 activation in CD5+CD1d+ Bregs and in the NOD mouse model can be activated with LPS (TLR4), resulting in TGFβ production, which inhibits Th1 responses and diabetes progression." (PMID 34616408, 2021). "We created a model that included six predictors of AKI: four (history of diabetes, BUN to creatinine ratio, CRP, and osteopontin) had a positive association with AKI risk; while two (CD5 antigen‐like and Factor VII) had a negative association with AKI risk." (PMID 30582197, 2019).
lung cancer (7 papers, 2017 to 2025). A malignant neoplasm involving the lung. "In contrast, down-regulation of CD5 expression in tumor-infiltrating lymphocytes was reported to improve the anti-tumor response in lung cancer patients." (PMID 35983088, 2022). "In a lung cancer study related to PD-1 and CD5, it was stated to have an antitumor effect." (PMID 36514573, 2022). "Downregulated expression of CD5 in tumor-infiltrating lymphocytes has been shown to provide antitumor effects in patients with lung cancer, and the decrease in serum concentration seen in the present study could reflect this as well." (PMID 35682983, 2022). "Furthermore, TILs with low CD5 expression isolated from lung cancer patients exhibited increase cytotoxic activity compared to CD5+ TILs." (PMID 33584650, 2020). "This is consistent with a report of increased anti-tumor cytolytic activity in T cells with low CD5 levels where TILs isolated from lung cancer patients exhibited differential anti-tumor activity where CD5 levels were negatively correlated with that anti-tumor activity." (PMID 33584650, 2020). "In tumor-infiltrating lymphocytes (TILs) isolated from lung cancer patients, CD5 levels were negatively correlated with anti-tumor activity and tumor‐mediated activation-induced T cell death, suggesting that CD5 could impair activation of anti-tumor T cells." (PMID 33584650, 2020). "Among the markers expressed in TC, CD5, CD117, and CD205 are uncommonly expressed in primary lung cancers, thereby presenting these markers as possible candidates in the IHC panel of thymic tumors when differentiating primary lung cancers." (PMID 32640732, 2020). "Furthermore, higher CD5 and CD6 expression predicts favorable outcomes for patients with nonsmall cell lung cancer (NSCLC) and plays positive roles in immune surveillance." (PMID 35983088, 2022).
lymphopenia (7 papers, 2008 to 2023). Reduction in the number of lymphocytes. "Homeostatic expansion, a process linked to CD5 expression level, is assumed to be driven by ‘self’ antigen when resources (e.g. IL-7) are abundant, as is the case in lymphopenia." (PMID 27881740, 2016). "Since Themis–/– mice have a higher proportion of CD44hi cells due to lymphopenia, we gated on CD44lo cells for our analysis of CD5, CD6 and CD44 expression." (PMID 33897691, 2021). "It is well accepted that T cell clone-specific features such as CD5 levels correlate closely with the sensitivity to lymphopenia." (PMID 30792713, 2019). "Further, FIVPco infected puma display a more generalized response of lymphopenia expressed as a significant decline in total lymphocytes, CD5+ T-cells, and CD5- lymphocytes as well as a significant reduction in CD4+ T-cells." (PMID 18251995, 2008). "Murine studies identify a correlation between surface expression of CD5, a marker of TCR signal strength on naive CD4+ and CD8+ T cells, and the intensity of lymphopenia-induced proliferation." (PMID 37856221, 2023). "Ourdata demonstrate that under lymphopenia, donor lymphocytes form a population ofmemory-like CD8+ T cells with the phenotype CD122+CD5+CD49dhiCXCR3+that shares the phenotypic characteristics of true memory cells and suppressiveCD8+ T cells." (PMID 33959391, 2021). "The absolute numbers of CD19+CD5+CD1dhigh cells, CD19+CD24+CD38+ cells, and CD19+IL-10+ cells increased but not significantly in SLE patients when compared with healthy controls, which might be attributed to peripheral lymphopenia in SLE patients during flares." (PMID 24551101, 2014).
splenic marginal zone lymphoma (7 papers, 2015 to 2025). Splenic marginal zone lymphoma is a rare, indolent B-cell non-Hodgkin lymphoma characterized by abnormal clonal proliferation of mature B-lymphocytes with involvement in the spleen, bone marrow and, frequently, the blood. "In 2010, important papers characterizing CD5− and/or CD5+ splenic marginal zone lymphoma (SMZL) were published, one in Haematologica and the other in J Clin Exp Hematopathol." (PMID 26558117, 2015). "His personal medical history included an indolent splenic marginal zone lymphoma (SMZL) of Matutes score 2 (splenomegaly, CD5 negativity and CD23 positivity), diagnosed following an idiopathic pulmonary embolism in December 2019, with no previous history of lung disease." (PMID 34376184, 2021). "A 69-year-old male patient previously diagnosed with pulmonary embolism and splenic marginal zone lymphoma (Splenomegaly, Matutes 2/5, CD5 negative and CD23 positive), was admitted to the hospital with shortness of breath, fever and asthenia." (PMID 34376184, 2021).
breast carcinoma (6 papers, 2017 to 2025). "The use of a function-blocking anti-CD5 monoclonal antibody or knockout of CD5 inhibited tumor growth in a breast cancer mouse model by enhancing the capability of CD8+ T cells." (PMID 33907159, 2021). "A negative correlation was found between CD5 positivity and tumor grade in breast cancer patients." (PMID 33907159, 2021). "TILs (i.e., CD3, CD5, CD4, PD-1) are not predictive markers in breast cancer, according to the few studies that have assessed the prognostic effects of TIL subsets in patients with breast cancer." (PMID 39507608, 2024).
Immunodeficiency (6 papers, 2007 to 2025). Failure of the immune system to protect the body adequately from infection, due to the absence or insufficiency of some component process or substance. "The reduction in IgG3 and IgG4 immunoglobulin levels is mainly attributed to impairments in both T-cell function and the activity of non-clonal CD5− B cells, contributing significantly to the overall immune deficiency seen in these patients." (PMID 40937017, 2025). "We confirmed these results in the Eμ-TCL1 transgenic mouse model, which spontaneously develops CD19+CD5+ CLL-like disease and recapitulates immune dysfunction witnessed in patients." (PMID 38775157, 2024). "The current report highlights the importance of early diagnosis of CD5-positive DLBCL because of its poor prognosis and calls attention to the critical importance to identify immunodeficiencies because doing so affects the types of treatments available." (PMID 36827036, 2023). "As shown in a recent clinical trial, CAR-T therapy targeting CD5 is an attractive strategy in patients with r/r CD5+ T cell malignancies without resulting in a life-threatening immunodeficiency." (PMID 34274536, 2021).
inflammatory bowel disease (6 papers, 2013 to 2022). A spectrum of small and large bowel inflammatory diseases of unknown etiology. "In this context, Stat3 whose function is increased by CD5 deficiency had previously been described as a critical regulator of the Th17/Treg balance, particularly in inflammatory bowel disease." (PMID 35720357, 2022). "Our results demonstrate that chronic intestinal inflammation decreases the frequency of CD5+ B cells and leads to a sustained CD5- B cell-dominant condition, which may be involved in the pathogenesis of refractory inflammatory bowel diseases (IBD)." (PMID 26727001, 2016).
Lymphadenopathy (6 papers, 2012 to 2025). Enlargement (swelling) of a lymph node. "Four dogs presented with leukocytosis (range: 81,000–179,600 leukocytes/μL), no or moderate peripheral lymphadenopathy and an expanded population of small to intermediate CD3+CD5+CD8+MHCII+ lymphocytes on blood FCM, compatible with T cell chronic lymphocytic leukemia (T-CLL)." (PMID 41394920, 2025).
multiple sclerosis (6 papers, 2018 to 2026). A progressive autoimmune disorder affecting the central nervous system resulting in demyelination. "Since in humans CD5 expression correlates with inflammation and cellular injury, targeting the CD5 signalling pathway provides future therapeutic opportunities for—among other diseases—multiple sclerosis." (PMID 40853926, 2026). "Importantly, transcriptomic and proteomic analysis showed that CD5 expression correlates with an inflammatory immune profile in multiple sclerosis in serum as well as CSF." (PMID 40853926, 2026). "Here, we aimed to understand the role of the surface molecule CD5 and its intracellular interaction partner casein kinase 2 (CK2) in human Th17 effector function as well as their role in multiple sclerosis." (PMID 40853926, 2026).
periodontitis (6 papers, 2013 to 2026). An acute or chronic inflammatory process that affects the tissues that surround and support the teeth. "Stimulation with P. gingivalis LPS (a TLR4 agonist) and CpG increases the percentages of IL-10-expressing CD1dhi CD5+ B cells in P. gingivalis-associated ligature-induced experimental periodontitis." (PMID 41289041, 2025). "It was demonstrated that the adoptive transfer of CD1dhi CD5+B cells inhibited periodontal bone loss in P. gingivalis-associated ligature-induced experimental periodontitis, suggesting a regulatory role of B10 cells in periodontitis and a potential novel principle for treating periodontal diseases." (PMID 41289041, 2025). "Multiple regression analysis revealed that besides age (p = 0.009), the double negative (CD27-IgD-) subset of CD5+ memory B cells was related to periodontitis, while total CD5+ B cell levels remained unchanged." (PMID 41708693, 2026). "CD5+ B cells, known for their autoreactive potential and role in bone resorption, have been previously found elevated in advanced periodontitis." (PMID 41708693, 2026). "This B cell subset referred as to autoreactive CD5+ B cells was inconsistently reported in periodontitis patients." (PMID 29447240, 2018). "Although the CD5+ B cell distribution appeared similar the SP group and the controls (9.2±5.3% for SP patients vs. 9.0±2.6% for NoP controls), we analysed this subset previously reported to be higher in gingival tissue of periodontitis patients." (PMID 29447240, 2018). "As a result, the ratio of CD5+ T cells and FOXP3+ Tregs increased in the periodontitis pre-treatment group." (PMID 36329504, 2022). "It was also demonstrated that there was an increase in the number of autoreactive CD5+ B cells in periodontitis lesions, and the CD5+ B cells produced more IgM and IgG antibodies to collagen in vitrothan did CD5− B cells." (PMID 24151615, 2013).
viral infections (6 papers, 2017 to 2024). "Together these findings demonstrate that B-1 cells accumulate in draining lymph nodes at the site of both, bacterial and viral infections, where they lose CD5 expression and become the main source of B-1 derived secreted IgM." (PMID 31433296, 2019). "As for CD5, targeting CD6 in certain viral infections could represent a new therapeutic approach, though further exploration is still needed." (PMID 33287301, 2020). "Further examination of lung T cells (CD3+CD5+ cells) showed no increase of IL-22 expression in L. paracasei-fed mice after 10 days of viral infection." (PMID 28931041, 2017).
Arthritis (5 papers, 2009 to 2024). Inflammation of a joint. "Moreover, CD5+ Fas ligand positive Breg cells were implicated in immune regulation in collagen-induced arthritis by promoting apoptosis in arthritis-associated T cells." (PMID 24945741, 2014). "Reduced numbers of splenic FasL+ CD5+ B cells correlated with increasing arthritis severity and decreased T-cell death in a T-cell receptor transgenic mouse model of collagen-induced arthritis." (PMID 19706160, 2009). "Among splenic lymphocyte populations, only the CD5+ B-cell subset displayed a decrease in relative numbers as arthritis severity increased." (PMID 19706160, 2009). "In another study, the relative number of IgG RF+ CD5+ B cells was reduced in arthritis patients whereas the number of IgG RF+ CD5- B cells was elevated." (PMID 19706160, 2009). "Among the cytokines produced by B cells, IL-6 and IL-10 are of particular interest because of their reported production by CD5+ B cells and their respective pro- and anti-inflammatory effects in arthritis models." (PMID 19706160, 2009). "The present findings suggest a novel regulatory role for CD5+ B cells on disease severity in a murine model of arthritis." (PMID 19706160, 2009). "Although antigen-dependent T-cell death has been demonstrated using purified CD5+ B cells in the murine model of Schistosoma mansoni infection, the present report is the first to show that T-cell death could be stimulated using a peptide derived from an arthritis-associated autoantigenic peptide." (PMID 19706160, 2009). "The trend toward fewer total lymphocytes in the spleens of severely arthritic mice indicates that the absolute number of CD5+ B cells was also reduced with increasing arthritis severity." (PMID 19706160, 2009). "Perhaps the present findings of FasL expression on CD5+ B cells and the inverse correlation between total numbers of splenic CD5+ B cells and arthritis severity in mice can shed new light on these apparent contradictions." (PMID 19706160, 2009). "Flow cytometry analysis revealed an increase of CD19+IgM+CD5+ cell population in draining lymph nodes and an increase of CD19+CD21hiCD23hi (B regulatory) cells in APRIL-Tg mice with arthritis as well as an increase of IL-10 and CXCL13 production in vitro." (PMID 38691538, 2024). "Differences in arthritis severity correlated with a reduction in the percentage of CD5+/CD19+ splenic B cells but not CD5-/CD19+ B cells or T cells." (PMID 19706160, 2009).
asthma (5 papers, 2020 to 2024). "Another male-specific pQTL rs11207327 linked with CD5 levels also modulates the expression of genes (JUN, KRT79, TACSTD2), and it is associated with diseases and traits (Asthma, self-reported haemorrhoids and treatment with estriol product)." (PMID 38326779, 2024). "In addition, we further assessed Breg cells (CD19+CD1d+CD5+) as a negative regulator of immunity in asthma and SCIT groups." (PMID 34804031, 2021). "Among these pathways, hematopoietic cell lineage is closely related to asthma, and the mRNAs enriched in this pathway included FCER2A, GP1BA, IL-7, and CD5." (PMID 34737744, 2021).
B-cell prolymphocytic leukemia (5 papers, 2014 to 2025). A neoplasm of prolymphocytes affecting the blood, bone marrow, and spleen. "Moreover, this entity also absorbs all cases previously termed CD5-negative B-prolymphocytic leukaemia (B-PLL) per WHO-HAEM4R." (PMID 35732829, 2022).
Castleman disease (5 papers, 2012 to 2025). Castleman disease (CD) is a benign lymphoproliferative disorder that may present as a localized or multicentric form. "Histological and immunohistochemical analysis confirmed the diagnosis of Castleman’s disease: staining for CD3, CD5, CD10, CD20, CD23, CD79 and Ki-67 was strongly positive in the germinal-center-like structures." (PMID 24612848, 2014).
cutaneous T-cell lymphoma (5 papers, 2021 to 2024). "Targeting CD5 with immunoconjugates linked to cytotoxic molecules had been used in clinical trials for cutaneous T-cell lymphoma." (PMID 39462383, 2024). "Previous studies imaging cutaneous T-cell lymphoma with [111In]In-T101, an anti-CD5 labeled antibody, showed prominent uptake in the spleen and nodes but no specific localization in the bowel." (PMID 36028577, 2022). "Monoclonal antibodies against CD5 have also been investigated and shown encouraging results against cutaneous T-cell lymphoma and T-ALL." (PMID 34035409, 2021). "Immunohistochemical results showed positivity for CD3, CD4, CD5, CD7, and CD8, indicating cutaneous T-cell lymphoma (CTCL) Sezary Syndrome." (PMID 40034934, 2024).
depression (5 papers, 2008 to 2025). "CD5 and CD8A are expressed on T cells which have been implicated in the pathogenesis of depression." (PMID 39799156, 2025). "Furthermore, a reduction of CD5 surface expression on transitional B-cells was correlated with severe depression." (PMID 38020762, 2023). "More recently, regulatory B cell populations, such as IgD–CD27+ naïve B cells, CD1d–CD5+ B cells, and CD24–CD38hi transitional B cells, are reported to be diminished in individuals with severe depression." (PMID 41356500, 2025).
lupus nephritis (5 papers, 2014 to 2023). Glomerulonephritis in the context of systemic lupus erythematosus. "Patients with new-onset lupus nephritis had a decrease in CD19+CD5+CD1dhighIL-10+ Bregs and restored Breg deficiency in patients who respond to immunosuppressive medications." (PMID 37771588, 2023). "Second, several CD5, CD6, and/or CD166/ALCAM gene variants have been associated with different IMIDs, such as RA, lupus nephritis, MS, psoriasis, Behçet's disease, and IBD." (PMID 35372412, 2022). "Association studies of CD5 variation in SLE show that the rs2241002C (Pro224) and rs2229177C (Ala471) alleles are associated with the development of lupus nephritis, which represents a severe form of the disease." (PMID 34070159, 2021). "A statistically significant increase of the CD5 CC haplotype frequency in SLE nephritis patients compared with controls group (p = 7.0×10−4, OR = 1.52, CI 95% = 1.18–1.95) was observed." (PMID 25402503, 2014). "Thus, the CD5 rs2241002C allele and the minor CD5 rs2241002T-rs2229177C haplotype, previously associated with a more aggressive form of SLE (lupus nephritis), showed association with anti-Ro/anti-La antibody positivity, and with anemia and thrombocytopenia, respectively." (PMID 35372412, 2022).
prolymphocytic leukemia (5 papers, 2021 to 2025). A mature B- or T- cell leukemia with progressive clinical course. "T-cell prolymphocytic leukemia (PLL) cells were characterized by homogenously moderate CD2, CD5, and CD7, variable loss of surface CD3, moderate-to-dim CD26, heterogeneous CD25, and moderate TCL1." (PMID 35299754, 2022).
Sjögren’s syndrome (5 papers, 2016 to 2025). "The sample size is relatively small, and further research is needed to expand the sample size, and the role of CD19+CD5+CD1d+ B cells in the occurrence and development of Sjogren’s syndrome needs further study." (PMID 40678132, 2025). "Logistic regression analyses of CD5 and CD6 SNPs association with anti-Ro/La antibodies, neutropenia, leukopenia, and peripheral nervous system (PNS) EULAR Sjögren's syndrome disease activity index (ESSDAI) activity." (PMID 35372412, 2022).
tuberculosis (5 papers, 2015 to 2025). A chronic, recurrent infection caused by the bacterium Mycobacterium tuberculosis. "Similarly, several paper also reported that peripheral blood circulating Bregs with CD19+CD1d+CD5+ phenotype were increased in patients with tuberculosis." (PMID 36761174, 2022).